CHST11 (carbohydrate sulfotransferase 11)
Diseases named in the same sentence as CHST11 in open-access papers (continued):
Sharing a sentence is not in itself a finding about the gene and the disease.
tumor (18 papers, 2011 to 2025). "Immune infiltration and m6A methylation analysis suggested the association of CHST11 with immune cell abundance in the tumor microenvironment and specific methylation patterns in ccRCC." (PMID 38565604, 2024). "CHST11 may be important in tumor-associated VCAN sulfation patterns, especially in early stromal changes." (PMID 39098880, 2024). "Moreover, the expression of Ki67 was elevated in CHST11-deficient cells, further suggesting CHST11 as a tumor suppressor in DLBCL." (PMID 37076815, 2023). "However, the data indicate that the expression of the CHST11 gene in tumor cells is associated with synthesis of P-selectin ligands and a metastatic phenotype." (PMID 21658254, 2011). "Key nodes, including CHST11 and VCAN, were associated with ECM sulfation, tumor invasiveness, and immune evasion." (PMID 40507957, 2025). "Integrated analysis of GTEx (normal, n = 171) and TCGA (tumor, n = 179) datasets revealed higher expression of CHST11, SLC16A1, RHOF, MAN1C1, SPRR1B, and ANO6 in tumors." (PMID 41346619, 2025). "Regarding paired tissues, the CHST11 gene expression level was higher in tumor tissues (n = 72) than in normal tissues (n = 72); these findings were consistent with those of nonpaired tissues (P < 0.001)." (PMID 38565604, 2024). "By using the TISIDB database, Spearman’s correlation analysis was performed between the CHST11 expression level and tumor lymphocytes, tumor immunostimulators, tumor immunoinhibitors, and major histocompatibility complex (MHC) proteins." (PMID 38565604, 2024). "The results showed a significant correlation between CHST11 and certain tumor immunostimulators (CD28, IL2RA, and TNFSF13B), tumor immunoinhibitors (CD96 and LGALS9), and MHC proteins (HLA-DRA and HLA-DMB)." (PMID 38565604, 2024). "Following the analysis of the downloaded TCGA-KIRC datasets, the results indicated that the CHST11 gene expression level was higher in tumor tissues (n = 541) than in normal tissues (n = 72)." (PMID 38565604, 2024). "In HCC group, 77 samples showed high CHST11 expression and 13 samples showed low CHST11expression, while in adjacent non‐tumor group, 21 samples showed high CHST11 expression and 69 samples showed low CHST11 expression." (PMID 36062845, 2023). "Gene functional enrichment analyses indicated that CHST11 modulated pathways related to tumor growth, metastasis and immune regulation." (PMID 36062845, 2023). "We first found that immune cells and stromal cells were significantly elevated in tumor samples with high CHST11 expression." (PMID 36062845, 2023). "Simultaneously, we recruited 56 multi‐center datasets involving in 3110 HCC samples and 2016 non‐tumor samples from 12 countries around the world to further validate the expression of CHST11 mRNA in HCC." (PMID 36062845, 2023). "Together, these data revealed that CHST11 suppressed tumor growth, and KIAA1429 exerted a tumor-promoting effect by inhibiting expression of CHST11 in DLBCL." (PMID 37076815, 2023). "In conclusion, the present study revealed that CHST11 facilitated tumor proliferation and metastasis of HCC." (PMID 36062845, 2023). "At the single-cell level, tumor cells expressed low levels of CHST11 compared with ALDH3B1, EGFR, ERAP2, MSLN, and NCEH1." (PMID 37251940, 2023). "Here, our study was the first to reveal the in vitro and in vivo anti-tumor roles of CHST11 in DLBCL." (PMID 37076815, 2023). "Knockdown of CHST11 resulted in remarkable enhancement in tumor volumes and acceleration of tumor growth rates." (PMID 37076815, 2023). "Functional enrichment analyses indicated that these genes not only participated in tumor growth and metastasis‐related pathways, but also participated in immune‐related pathways, indicating the potential immune regulatory role of CHST11 in HCC." (PMID 36062845, 2023). "The results indicated that FABP4, ERMN, and CHST11 were overexpressed in CRC tumor tissues compared with normal tissues." (PMID 34294834, 2021).
tumor (continued). "Our current and previously published data suggest that CHST11 expression plays a role in tumor progression and metastasis." (PMID 25586191, 2015). "CSPG4 was elevated 3.2-fold (P < 0.02) in tumor tissue over normal tissue among 14 subjects, while CHST11 was elevated 1.8-fold (P = 0.034) in tumor over normal among 15 subjects." (PMID 21658254, 2011). "Our data show for the first time that P-selectin can bind to tumor cells via CSPG4 and that CHST11 expression is linked to P-selectin-reactive cell surface CS/DS-GAGs." (PMID 21658254, 2011). "CSPG4 and CHST11 expression showed an increase in tumor tissue over normal tissue in 10 out of 14 sample pairs and 8 out of 15 sample pairs, respectively." (PMID 21658254, 2011). "Additionally, the elevated expression of CHST11 was strongly correlated with higher clinical stages of the tumor (P < 0.01)." (PMID 38565604, 2024). "Since KIAA1429 induced downregulation of CHST11 expression, we explored whether this regulation involved the tumor-promoting role of KIAA1429 in DLBCL." (PMID 37076815, 2023). "The expression of CHST11 in tumor tissue may also be controlled by DNA methylation similar to that observed in cell lines." (PMID 25586191, 2015). "The data further suggest that overexpression of both CSPG4 and CHST11 genes in tumor cells may contribute to a superior metastatic potential." (PMID 21658254, 2011). "Thereby, the expression of CHST11 may correlate better with the tumor cells' aggressive phenotype than does the prevalence of any particular CS isomers." (PMID 21658254, 2011). "In addition, CSPG4 and CHST11 were over-expressed in tumor-containing clinical tissue specimens compared with normal tissues." (PMID 21658254, 2011). "Therefore, concerted upregulation of CSPG4 and CHST11 may induce expression of a unique molecular entity that may increase the metastatic capabilities of tumor cells." (PMID 21658254, 2011). "In DLBCL, Hippo–YAP pathway inactivation via carbohydrate sulfotransferase 11 (CHST11) and KIAA1429/YTHDF2 repression inhibits cell proliferation and tumor growth and induces cell cycle arrest and apoptosis." (PMID 39802639, 2025). "We scored CHST11 expression in the 90 HCC tissues and matched non‐tumor tissues with IRS system." (PMID 36062845, 2023). "Since KIAA1429 negatively regulated CHST11 and activation of YAP, we further explored whether this regulation was responsible for the tumor-promoting effects of KIAA1429 in DLBCL." (PMID 37076815, 2023). "In this study, we presented for the first time that the absence of microenvironmental Gal-3 modulated negatively the carbohydrate sulfotransferase 11 (CHST11) mRNA levels in the primary tumors, indicating that the tumor cell line behavior can be modified by the tumor microenvironment." (PMID 31949431, 2019). "Our findings also potentially reveal an unexpected role for CHST11 and/or MIR3922 as tumor suppressors whose disruption may contribute to malignant lymphoproliferative disease." (PMID 26436107, 2015). "Interestingly, in the absence of Gal-3 in the tumor microenvironment (Lgals3−/−), there was a reduction in the mRNA levels of CHST11 in 4T1-shRNA-Gal-3-derived tumors in comparison with 4T1-scramble-derived tumors." (PMID 31949431, 2019). "Other ofCS modification enzymes (DSE, CHST11, and CHST13) were not differentially expressed between normal and tumor samples." (PMID 34966741, 2021). "Our findings also support the hypothesis that CHST11 and/or MIR3922, a microRNA whose function has not previously been described, may act as tumor suppressors in the lymphocyte lineage." (PMID 26436107, 2015).
adenocarcinoma (1 paper, 2022). A common cancer characterized by the presence of malignant glandular cells. "The top three genes upregulated after castration as compared to adenocarcinomas were the heparan sulfate sulfotransferases HS3ST5 and HS6ST2, and the chondroitin sulfate sulfotransferase CHST11." (PMID 35963852, 2022).
inflammation (1 paper, 2024). Aberrant reaction of the microcirculation characterized by movement of fluid and leukocytes from the blood into extravascular tissues. "In the mouse model of carrageenan-induced systemic inflammation, increases in phospho-p38 MAPK and expression of CHST15 and CHST11 and declines in DNA-E2F binding and ARSB expression occurred in the lung, similar to the observed effects in this SPRBD model of COVID-19 infection." (PMID 38355690, 2024).
CHST11 also shares sentences with these, for which no sentence is quoted: glioblastoma (2 papers); viral infection (2); achondrogenesis type IB (1); atelosteogenesis type II (1); bladder urothelial carcinoma (1); cholangiocarcinoma (1); chondrosarcoma (1); colon cancer (1); dwarfism (1); esophageal carcinoma (1); head and neck squamous cell carcinoma (1); hematologic malignancies (1); hip osteoarthritis (1); liver cancer (1); liver fibrosis (1); lymphoma (1); lymphoproliferative disorder (1); mucopolysaccharidoses (1); multiple myeloma (1); neuroblastoma (1); neurodegenerative disease (1); neurodevelopmental disorder (1); osteosarcoma (1); pancreatic adenocarcinoma (1); pulmonary fibrosis (1); Raine syndrome (1); skeletal dysplasia (1); stomach adenocarcinoma (1); tauopathy (1); Thyroid carcinoma (1).